RNU6-849P (RNA, U6 small nuclear 849, pseudogene)
Gene: Small nuclear RNA gene on chromosome 7 (79,912,104 to 79,912,208, reverse strand). Ensembl gene ENSG00000206818.
Homologues: Orthologues: chimpanzee U6 (100% identical), macaque U6 (94% identical), guinea pig U6 (86% identical). Paralogues in human: RNU6-1145P (87% identical), RNU6-38P (87% identical), RNU6-1316P (86% identical), RNU6-140P (85% identical), RNU6-16P (85% identical), RNU6-25P (85% identical), RNU6-29P (85% identical), RNU6-393P (85% identical), RNU6-41P (85% identical), RNU6-46P (85% identical), RNU6-480P (85% identical), RNU6-639P (85% identical), and 1286 more.